PDK1 (pyruvate dehydrogenase kinase 1)
Diseases named in the same sentence as PDK1 in open-access papers (continued):
Sharing a sentence is not in itself a finding about the gene and the disease.
lung cancer (43 papers, 2013 to 2025). A malignant neoplasm involving the lung. "In this study, we investigated the association between PDK1 expression and the development of drug resistance in lung cancer tissue samples." (PMID 38689087, 2024). "Previous studies have shown that both G6PD and PDK1 are associated with cisplatin resistance in lung cancer and that their inhibition or downregulation can sensitize cancer cells to cisplatin treatment." (PMID 38351531, 2024). "Recent evidence indicated that PDK-1 may be involved in lung cancer, however, the function and underlying mechanism of PDK-1 is remaining unclear." (PMID 30988063, 2019). "Recently, evidence suggested that pyruvate dehydrogenase kinase-1 (PDK-1) implicated in lung cancer, however, the specific function and underlying mechanism of PDK-1 in NSCLC remains unknown." (PMID 30988063, 2019). "TMEM116 promotes cell migration and invasion, via the regulation of the PDK1-AKT-FOXO3A pathway in lung cancer." (PMID 37367036, 2023). "Other studies have shown that miR‐503 inversely regulates lung cancer progression by inhibiting different targets including PDK1 (pyruvate dehydrogenase kinase 1) and LARP1 (La‐related protein 1) respectively." (PMID 37212485, 2023). "Pyruvate dehydrogenase kinase 1 (PDK1) induces the Warburg effect to improve the migration of lung cancer cells." (PMID 35326412, 2022). "Atractylenolide I inhibits the growth of lung cancer cells by inhibiting PDK1 and LncRNA HOTAIR-mediated EZH2 gene expression." (PMID 34335248, 2021). "In this study, we demonstrated that inducing degradation of NRF2 by inhibiting PDK1 is a promising strategy to combat lung cancer." (PMID 34211631, 2021). "Among the four isoforms, PDK1 has been extensively studied in cancer and its upregulation has been reported in a variety of tumors including head and neck cancer and breast and lung cancer." (PMID 34439291, 2021). "In this study, we revealed that IQ isolated from S. cerebriformis induced the apoptosis of lung cancer cells by inhibiting the activity of PDK1." (PMID 32825675, 2020). "Liu and Yin indicated that PDK-1 was highly expressed in lung cancer tissue, and promotes lung cancer cell proliferation, migration and Warburg effect in lung cancer." (PMID 30988063, 2019). "miR-145 inhibits lung cancer cell migration and invasion by targeting PDK1 via the mTOR signaling pathway." (PMID 29340099, 2017). "An elevated expression of PDK1 enzyme has been reported in several aggressive cancer types, such as gastric cancer, lung cancer, and myeloma." (PMID 29117193, 2017). "MiR-138 also acts as a potential tumor suppressor that inhibits cell proliferation by targeting PDK1 in non–small cell lung cancer (NSCLC) cells." (PMID 27019355, 2016). "Together, this suggested that ciglitazone not only inhibited growth but also increased apoptosis of lung cancer cells through, at least in part, the inhibition of PDK1." (PMID 24925061, 2014). "We further tested the role of the transcription factors in mediating the effect of ciglitazone on PDK1 expression in human lung carcinoma cells." (PMID 24925061, 2014). "Furthermore, in lung cancer, BAG4 has been implicated in promoting proliferation, invasion, metastasis and drug resistance, functioning within the PI3K/PDK1/AKT and RAF/MEK/ERK signaling pathways." (PMID 40870378, 2025). "Finally, we sought to provide novel insights into the fundamental mechanisms contributing to anticancer drug resistance, with a particular emphasis on positioning PDK1 as a prospective molecular target for therapeutic interventions in lung cancer." (PMID 38689087, 2024). "The scientists concluded that targeting PDK1 could be a promising method for overcoming osimertinib resistance in lung cancer, potentially leading to more effective treatments for this type of cancer." (PMID 38689087, 2024). "Some putative miRNAs could regulate the progression of lung cancer through the PDK1/PI3K/AKT pathway." (PMID 37107587, 2023).
lung cancer (continued). "LA (α-lipoic acid) is a novel PDK1 inhibitor for the treatment of lung cancer." (PMID 34211631, 2021). "Moreover, the inhibition of PDK1 was reported to enhance the anticancer effects of EGFR tyrosine kinase inhibitors (TKIs) in lung cancer." (PMID 34439291, 2021). "As we have stated, dichloroacetate, which inhibits PDK1 and restores drug sensitivity in paclitaxel-resistant lung cancer cells (A549), increases cytosolic citrate, while ACLY inhibition, which reduces tumor growth in various models, likely increases citrate level." (PMID 34205414, 2021). "Thus, we suggest that IQ significantly induced mitochondrial ROS production by inhibiting PDK1 activity and thereby induced apoptotic cell death in the A549 lung cancer cells." (PMID 32825675, 2020). "Although the effects of PDK-1 on lung cancer cell biology have been reported, the molecular mechanism is still unknown." (PMID 30988063, 2019). "Accumulating evidence indicated that the key enzyme PDK-1 was involved in metabolic reprogramming of tumors and was highly expressed in types of cancer, such as breast cancer, head and neck squamous cancer, myeloma, gastric cancer, and lung cancer." (PMID 30988063, 2019). "PDK1 gene has been assoiated with poor differentiation of late stage lung cancer." (PMID 26684827, 2015). "In an effort to explore the anti-tumor effects of ciglitazone on potential targets, we turned our attention to 3-phosphoinositide-dependent protein kinase 1 (PDK1), a master regulator of signal cascades that is involved in suppression of apoptosis and promotion of tumor growth including lung cancer." (PMID 24925061, 2014). "This study provides a novel mechanism by which the antidiabetic drug inhibits human lung cancer cell growth, and targeting the PDK1 may be a potential therapeutic strategy for inhibition of lung cancer growth." (PMID 24925061, 2014). "In an effort to explore the anti-tumor effects of NAC on potential targets, we turned our attention to 3-phosphoinositide-dependent protein kinase 1 (PDK1), a master regulator of signal cascades that are involved in suppression of apoptosis and promotion of tumor growth including lung cancer." (PMID 23867003, 2013). "We have found that NAC inhibited NSCLC cell proliferation through reduction of PDK1, a kinase and master regulator of a number of downstream signal cascades that are involved in suppression of apoptosis and promotion of tumor growth including lung cancer." (PMID 23867003, 2013). "Based on our identified miRNA-regulated molecular machinery, an inhibitor of PDK1/Akt BX-912, an anthracycline antibiotic daunorubicin, and a multi-targeted protein kinase inhibitor midostaurin were discovered as potential repositioning drugs for treating lung cancer." (PMID 37190222, 2023). "Some other drugs for lung cancer therapy under trial include dichloroacetate (DCA), which is a pyruvate dehydrogenase kinase 1 (PDK1) inhibitor." (PMID 38785748, 2024). "In lung cancer cells, it has been reported that miR‐503 targets PI3K p85, IKK‐β, and PDK1 to suppress invasive characteristics." (PMID 37212485, 2023). "Knockdown TMEM116 also reduced the protein level of PDK1, p-AKT and FOXO3A of lung cancer A549 cells." (PMID 37367036, 2023). "We further analyzed the expression of TCRP1, p-PDK1 and p-AKT1 in primary lung cancer and glioma tissue samples by immunohistochemistry analysis." (PMID 28436990, 2017). "More importantly, we found that the expression of TCRP1 has a positive correlation with p-PDK1, as well as p-AKT1 in human lung cancer and glioma tissue samples." (PMID 28436990, 2017). "Spearman correlation analysis showed that the expression of TCRP1 has a positive correlation with p-PDK1, as well as p-AKT1 in lung cancer and gliomas tissues." (PMID 28436990, 2017). "In a word, SODD may promote proliferation, invasion, metastasis, and drug resistance of lung cancer cells, where PI3K/PDK1/AKT and RAF/MEK/ERK signaling play a considerable role." (PMID 37107587, 2023).
lung cancer (continued). "Overexpression of lncRNA-IGFBP4–1 via targeting HK2/PDK1/LDHA could affect energy metabolism and promote lung cancer progression." (PMID 33123468, 2020). "Although we have only investigated the anti-lung cancer activity of 9za in vitro until now, we can anticipate the potent anti-tumor effect in vivo based on that 9za is a dual MEK/PDK1 inhibitor and has stronger anti-cancer efficacy than the single MEK/PDK1 inhibitor." (PMID 33072436, 2020). "Absence of p38α catalytic activity leads to further Pdk1 activation (independent of Akt and Erk activity), enhancing the survival and proliferation of the more malignant lung cancer cells." (PMID 24265727, 2013). "Besides, SH2B1 knockout led to downregulation of GLUT1, PDK1, and LDHA in lung cancer cells." (PMID 41410190, 2025).
pancreatic cancer (37 papers, 2012 to 2025). "PDK1 is dominantly found in pancreatic islets and it has been described that inhibition of PDK1 influence microbiota and metabolomic profile in pancreatic cancer xenograft mice." (PMID 38425123, 2024). "In pancreatic cancer cells, hypoxia induces the upregulation of circular PDK1, which activates the host gene PDK1." (PMID 37408250, 2023). "Hypoxia-induced repression of pyruvate dehydrogenase activity was mediated by pyruvate dehydrogenase kinase 1 in pancreatic cancer cells." (PMID 35053572, 2022). "In one study, transiently silenced RelA increased Gemcitabine-induced cell killing, while in another study selective knockdown of RelA in combination with pyruvate dehydrogenase kinase (PDK1/2) enhanced radiation sensitivity of pancreatic cancer cells." (PMID 35402225, 2022). "Pancreatic tumor tissues from KC mice revealed a loss of KLF10 immunolabeling and elevated PKM2 and PDK1 expression." (PMID 34702956, 2021). "This study identified PDK1 as a novel potential target to develop new treatment strategies in pancreatic cancer." (PMID 31088502, 2019). "As we recently reported that PDK1 inhibition is able to reduce pancreatic cancer cell growth, we tested IB35 and SA16 on a panel of pancreatic cancer cell lines." (PMID 31683659, 2019). "Treatment with specific inhibitors of PDK1 impaired anchorage-dependent and anchorage-independent growth of pancreatic cancer cell lines, as well as pancreatic tumour growth in a xenograft model." (PMID 31088502, 2019). "Here, we tested two drugs displaying dual inhibitory activity towards PDK1 and Aurora kinase A in a panel of pancreatic cancer cell lines and in two in vivo models of pancreatic cancer." (PMID 31683659, 2019). "We next tested the antitumorigenic activity of the dual PDK1/Aurora kinase inhibitors in vitro by investigating their effect on anchorage-independent growth (3D growth) of pancreatic cancer cells." (PMID 31683659, 2019). "Taken together our data provide important information on the mechanisms by which two dual PDK1/Aurora kinase inhibitors impair tumor progression in pancreatic cancer models." (PMID 31683659, 2019). "We have recently found that treatment with PDK1-specific inhibitors decreased anchorage-dependent and anchorage-independent growth of pancreatic cancer cell lines, and pancreatic tumor growth in a xenograft model." (PMID 31683659, 2019). "We next determined the effect of the dual PDK1/Aurora Kinase A inhibitors on cell growth using a panel of five human pancreatic cancer cell lines displaying distinct genetic complexity, and on one non-malignant human pancreatic duct cell line (hTERT-HPNE)." (PMID 31683659, 2019). "In this study, we confirmed the relationship between TNS2 expression and the expression of Axl, IRS-1, PDK1 and Glut4 in pancreatic cancer patients." (PMID 30419905, 2018). "In this murine model of pancreatic cancer PDK1 has been found to play an important role in both pancreatic cancer initiation and progression." (PMID 28287465, 2017). "Several in vitro and in vivo studies have shown that pancreatic miRNA-375 directly targets PDK1, plays key roles in the glucose regulation of insulin gene expression and β-cell growth and is down-regulated in pancreatic carcinoma." (PMID 27276676, 2016). "For example, several studies reported that pancreatic miRNA-375, which directly targets PDK1, plays key roles in the glucose regulation of insulin gene expression and β-cell growth and was evidently downregulated in pancreatic carcinoma." (PMID 27276676, 2016). "For miR-375, in vitro and animal studies showed that pancreatic miRNA-375 directly targets PDK1, plays key roles in glucose regulation of insulin gene expression and β-cell growth and is down-regulated in pancreatic carcinoma." (PMID 25255814, 2014).
pancreatic cancer (continued). "Similar results were shown in pancreatic cancer cells, where miR-375 suppressed cell growth and induced apoptosis by negatively regulating the expression of 3-phosphoinositide-dependent protein kinase 1 (PDK1)." (PMID 37443682, 2023). "To verify whether FUT11 promoted the proliferation of pancreatic cancer via increasing the expression of PDK1, we overexpressed PDK1 in FUT11 knockdown PC cells." (PMID 34221996, 2021). "Among the 700 interacted proteins with FUT11, PDK1 has been revealed as an oncogene in pancreatic cancer, indicating that the effect of FUT11 on PC cells might be associated with PDK1." (PMID 34221996, 2021). "Whether PDK1 might act specifically downstream of mutant KRas in the context of pancreatic cancer remains to be established." (PMID 31088502, 2019). "Both PDK1 and Aurora kinase are two emerging targets in pancreatic cancer." (PMID 31683659, 2019). "Therefore, we decided to characterize the preclinical activity of our recently synthesized double PDK1/Aurora kinase inhibitors on pancreatic cancer, namely SA16 and IB35." (PMID 31683659, 2019). "Moreover, we found a positive relationship between TNS2 expression and the expression of Axl, IRS-1, PDK1 and Glut4 in pancreatic cancer patients." (PMID 30419905, 2018). "Additionally, it seems that a specific micro-RNA, miR-375 is the missing link connecting these two proteins and its expression is significantly different in normal versus pancreatic cancer tissues, correlating also with PDK1 expression levels." (PMID 29064423, 2017). "In addition, Cre-mediated deletion of the PI3K effector Pdk1 in Kras-initiated pancreatic tumours reduces the induction of p19ARF38." (PMID 27585860, 2016). "Moreover, PDK1 has been suggested as a viable target in head and neck cancer, multiple myeloma, pancreatic cancer, and colorectal cancer." (PMID 26318166, 2015). "Increased PDK1 expression has also been reported in 45% of patients with acute myeloid leukemia, and PDK1 seems to be a viable target in head and neck cancer, multiple myeloma, pancreatic cancer, and colorectal cancer." (PMID 24739482, 2014). "Elevated STAMBP in pancreatic cancer has been found to interact with E2F1, preventing its degradation and promoting the PDK1-mediated Warburg effect, which contributes to chemotherapy resistance." (PMID 40149859, 2025). "Specifically, miRNA-375 targets directly PDK1 and miRNA-200c targets MUC4 (Mucin 4), influencing epithelial–mesenchymal transition and metastatic potential in pancreatic cancer cells." (PMID 39200178, 2024). "Pancreatic tumor cells specifically over-express glycolytic enzymes, such as hexokinase 2 (HK2), pyruvate dehydrogenase kinase isozyme 1 (PDK1) and lactate dehydrogenase A and B (LDHA, LDHB) compared to normal pancreatic cells." (PMID 36614196, 2023). "In contrast to glycolysis, phosphorylated pyruvate dehydrogenase kinase 1 (PDHK1) inhibits the pyruvate dehydrogenase (PDH) complex, suppressing mitochondrial OXPHOS in pancreatic cancer cells." (PMID 32122374, 2020). "In order to evaluate the possibility to use dual PDK1/Aurora kinase A inhibitors as potential in vivo therapeutics, we performed a xenograft experiment using HPAF-II human pancreatic cancer cell line." (PMID 31683659, 2019). "Phosphorylated Erk and its upstream regulator PDK1, were down-regulated and phosphorylation of JNK was increased after HNA treatment in two of the pancreatic cancer cell lines." (PMID 24952679, 2014). "E2F1, which was preferentially essential in pancreatic cancer cells, has been previously shown to regulate both pancreatic B-cell development and cancer growth by increasing the expression of PDK1 and PDK3 which results in increased aerobic glycolysis and growth in pancreatic cancers." (PMID 36727483, 2023).
pancreatic cancer (continued). "Additionally, we found that combination of sub-optimal concentrations of inhibitors selective for PDK1 and the class IB PI3K isoform p110γ inhibits pancreatic cancer cell growth and colonies formation more potently than each single treatment." (PMID 31088502, 2019). "Therefore, we further examined the correlation of TNS2 expression and expression of Axl, IRS-1, pyruvate dehydrogenase kinase 1 (PDK1) and glucose transporter type 4 (Glut4) in tissue of 33 patients with pancreatic cancer." (PMID 30419905, 2018). "Thus, Eser and coworkers have provided evidence that PI3K, as well as 3-phosphoinositide-dependent kinase 1 (PDK1) are activated in tumor pancreatic neoplasia (including preneoplastic lesions), as well as in KRAS-driven murine pancreatic cancer." (PMID 29156578, 2017). "Our research firstly demonstrated that Baicalein decreased phosphorylation of Akt at T-308 through targeting NEDD9-dependent PDK1 expression, but the target of Baicalein on the suppression of p-AKT at S-473 in pancreatic cancer cells requires further exploration." (PMID 28915595, 2017). "Our data implicate that hypoxia-induced FUT11 contributes to proliferation and metastasis of PC by maintaining the stability of PDK1, thus mediating activation of AKT/mTOR signaling pathway, and suggest that FUT11 could be a novel and effective target for the treatment of pancreatic cancer." (PMID 34221996, 2021). "In this study, two novel dual inhibitors targeting PDK1 and Aurora kinase A have been tested in a panel of pancreatic cancer cell lines and compared to non-malignant cells to check the effect of their activity on PI3K and Aurora kinase A pathways, and their potential as anticancer agents." (PMID 31683659, 2019). "Importantly, blockade of PI3K or PDK1 activity elicited a marked inhibition of KRAS-dependent metaplasia and tumorigenesis, thus suggesting also that the KRAS→PI3K→PDK1 pathway may represent a potentially important target in pancreatic cancer therapy." (PMID 29156578, 2017). "Further, PDK1 inactivation effectively attenuated the development of Kras oncogene-driven pancreatic cancer, but not NSCLC, further supporting the importance of PDK1 in tumor development, albeit, in select cancer types." (PMID 26684827, 2015).